TNF (tumor necrosis factor)
Diseases named in the same sentence as TNF in open-access papers (continued):
Sharing a sentence is not in itself a finding about the gene and the disease.
colon carcinoma (continued). "The increased levels of pro-inflammatory cytokines (TNF-& IL-1β), and tumor markers (CEA, CA19.9 and AFP) matched with a decrease in apoptotic biomarkers (CD4+) in colon cancer-bearing rats are in line with other earlier research." (PMID 36294905, 2022). "Moreover, reanalysis of single cell RNA-seq data of colon cancer revealed that TAMs increased activation of NO-related pathways, including protein nitrosylation and NO-mediated signal transduction, as well as inflammatory cytokine signalling, such as IL-6 and TNF-α." (PMID 35660630, 2022). "The addition of tumor necrosis factor α (TNF-α), interferon γ (IFN-γ), and interleukin-2 (IL-2) to human colon cancer cells resulted in the reduced expressions of the cell lines." (PMID 35814435, 2022). "Papila and colleagues compared serum values of NF-ƙB, PTX-3, IL-6, CRP, TNF-α, and sTRAIL (soluble TNF-related apoptosis-inducing ligand) and PCT (procalcitonin) in 40 individuals diagnosed with breast cancer, 40 with colon cancer, and 30 health controls." (PMID 36499628, 2022). "A TNF mutant with a reduced potency was generated for an IL-2-TNF dual immunocytokine and controlled tumor progression when targeted to EDA in colon carcinoma, LLC, sarcoma, and teratocarcinoma models." (PMID 33803078, 2021). "Additionally, TNF-α promotes phenotypic transition and increases the expression of EMT markers compared with TGF-β1 alone, which leads to the assumption that a pro-inflammatory tumor microenvironment enriched in TNF-α may accentuate TGF-β1-induced EMT in colon cancer cells." (PMID 34943943, 2021). "Dexmedetomidine suppressed the rapid increase of cytokine, TNF-α, and IL-6 levels in gastric cancer patients and decreased IL-6 and CRP levels and the inhibition of T-lymphocyte subsets in colon cancer patients undergoing radical surgery." (PMID 34300310, 2021). "TTP family mRNA levels (ZFP36, ZFP36L1 and ZFP36L2 mRNAs) were generally decreased and TTP-targeted cytokine mRNA levels (TNF, COX2, PPARR and RAB24 mRNAs) were relatively high in the colon cancer cells." (PMID 33723275, 2021). "TNFα in addition activates TGFβ-mediated EMT and EMT in colon cancer and lung epithelial cancer cell lines through activation of miR-21, miR-31, and miR-23a." (PMID 34220337, 2021). "Specifically, overexpression of PHD2 impaired MDSC recruitment due to a decrease in NF-κB activity that resulted in lower TNF and G-CSF expression, which are crucial cytokines for MDSC mobilization from colon cancer cells." (PMID 33673417, 2021). "LPEPS oral administration significantly down-regulated pro-inflammatory factors (IL-8, TNF-α, and IL-1β) and up-regulated anti-inflammatory factor (IL-10) levels in the serum of AOM/DSS-induced colon cancer mice." (PMID 34945611, 2021). "TROP2 expression enhances anchorage-independent growth in colon carcinoma cell lines and its activation of TROP2 by Tumor Necrosis Factor (TNF)-alpha induces cell migration and invasion." (PMID 32410997, 2020). "CyCl treatment suppressed the expression of NF-κB target genes, such as NF-κB inhibitor α and δ, TNF-α, IL-6, and IL-8, in TNF-α treated colon cancer cells." (PMID 32230772, 2020). "Further, we confirmed that miR-381-3p efficiently inhibited TNF-induced apoptosis in multiple human cancer cell lines including pancreatic cancer Panc-1 cells, gastric carcinoma MKN45 cells, and colon cancer SW620 cells." (PMID 32411707, 2020). "Treatment of an adenocarcinoma colon cancer cell line, COGA-1A, with 10 nM 1,25-dihydroxyvitamin D (1,25-OHD) inhibited the upregulation of COX-2 mediated by TNF-α by 37% after 12 h." (PMID 32422882, 2020). "Lactobacillus acidophilus EPS can inhibit the growth of Caco-2 colon cancer cells while EPS from L. gasseri can induce apoptosis in cervical tumor cells, also decreasing the production of TNF-α and increasing the IL-10 production thus controlling inflammation." (PMID 33193180, 2020).
colon carcinoma (continued). "Because miR-21 is positively involved in cell survival and TNF-α promotes necrosis, we found it interesting to analyze the presence of miR-21 in areas of TNF-α mRNA expression at the invasive front of colon cancers." (PMID 30999696, 2019). "Alongside this, it was revealed that long-term TNF-α treatment reduces the Pgp/ABCB1 transcript and protein levels in intrinsically Pgp-positive colon cancer cells, promoting sensitivity to chemotherapeutic drugs and, possibly, MDR reversal." (PMID 31137684, 2019). "To test a potential contribution of TOP1 or TOP2 on TNFα-induced expression of inflammatory genes, we measured the impact of specific TOP1 inhibitors on TNFα-triggered gene expression in human diploid colon cancer HCT116 cells." (PMID 31242600, 2019). "Neutrophils are a major source of TNFα, and it is likely that neutrophil-derived TNFα, downstream of HIF-2α activation plays an important role in inflammation-induced colon tumor growth." (PMID 31461847, 2019). "Incremental expression of proinflammatory cytokines such as NF-κB and TNF-α and overactivation of IL-6/STAT3 passage have been well determined to exercise definitive implication in the pathogenesis of UC and colon cancer." (PMID 31772601, 2019). "TNF-α, a well-known inflammatory cytokine contributing to cancer progression, dramatically stimulates miR-105 expression, inducing EMT in colon cancer." (PMID 30115896, 2018). "For the first time, we show that MMM induce MK2 phosphorylation in colon tumor cells and when added to tumors treated with MK2 inhibitor induce production of the known MK2-downstream cytokines IL-1β, IL-6, and TNF-α." (PMID 30298062, 2018). "The present investigation confirms the inhibition of TNF-alpha by zerumbone and the decrease in HCT116 Cell proliferation in controlling colon cancer." (PMID 29511228, 2018). "Concentration of TNFα was significantly decreased in all groups treated with ITF compared with control group, which development colon cancer." (PMID 28293641, 2017). "TNF-α-primed-hMSCs secrete high level of CCL5, which interacts with its receptor CCR1 expressed in colon cancer cells." (PMID 28542126, 2017). "We had previously demonstrated that MSCs pre-treated by inflammatory cytokines such as TNF-α and IFN-γ in the tumor microenvironment express higher levels of VEGF via the HIF-1α signal pathway and promote colon cancer growth by enhancing tumor angiogenesis." (PMID 29268703, 2017). "We constructed a model of the signalling network downstream of TNF α and EGF in HT-29 human colon carcinoma cells, formalizing the crosstalk that takes place between the pathways at different levels of cellular regulation." (PMID 27460034, 2016). "We used HT-29 human colon carcinoma cells to evaluate the role of TSPO and its drug ligands in tumor necrosis factor (TNF)-induced inflammation." (PMID 27054921, 2016). "We also showed the construction of an executable model of signalling events downstream of TNF α and EGF in human colon carcinoma cells." (PMID 27460034, 2016). "We show this by presenting ANIMO models for two case studies: Drosophila melanogaster circadian clock, and signal transduction events downstream of TNF α and EGF in HT-29 human colon carcinoma cells." (PMID 27460034, 2016). "In other cell systems, p38 MAPK mediates MMP-9 upregulation in response to several stimuli, including TNF-α and SDF-1/CXCR7 in bladder and ovarian, respectively, carcinoma cells, and clusterin/thrombospondin-1 in platelet-stimulated colon cancer." (PMID 27829220, 2016). "It was found that both IL-6 and TNF-α interact to induce TNF-R2 expression and function in colon cancer cells, suggesting that a specific microenvironment of multiple cytokines is required to induce TNF-R2, as found in IBD or IBD associated CRC." (PMID 26896068, 2016). "Elevated levels of IL-1β, IL-6, TNF-α, MCP-1 and PGE2 are therefore accepted as major prognostic indicators for the progression of colon cancer." (PMID 27507058, 2016).
colon carcinoma (continued). "Moreover, in colon cancer cells, tumor necrosis factor α (TNF-α), a proinflammatory cytokine that plays a pivotal role in IBD, was shown to upregulate the de novo pathway of sphingolipid biosynthesis, and it is conceivable that this effect could contribute to Cer and SM accumulation in IBD." (PMID 26880864, 2016). "Once activated, NFκB up-regulates the transcription of various proinflammatory mediators including TNF-α, IL-1β, IL-6, COX-2 and iNOS, which typically are overexpressed in colon cancer." (PMID 25763529, 2015). "Activation of the TNF-α or the NF-κB pathway is important especially in the development of HCC and colon cancer." (PMID 26296091, 2015). "Claudin-1 expression conferred resistance to anoikis in colon cancer cells in a Src-dependent manner, reduced apoposis of nasopharyngeal carcinoma cells and was also found to protect MCF-7 cells from TNF-α- and tamoxifen-induced death." (PMID 26083392, 2015). "We treated the colon cancer cell line COGA-1A for 6, 12, and 24 h with 1,25-dihydroxyvitamin D3 (1,25-D3), IL-6, TNFα, and with combinations of these compounds." (PMID 24120915, 2014). "D. candidum increased the body weights of the mice compared with the control group, and reduced the levels of the serum proinflammatory cytokines, IL-6, IL-12, TNF-α and IFN-γ, compared with the colon cancer control group." (PMID 24396476, 2014). "The inflammatory factor TNF-α is known to promote metastasis by enhancing EMT and invasiveness in colon cancer." (PMID 24386633, 2013). "IGF1 has been reported to amplify Fas antibody-induced apoptosis in human osteoblasts, to stimulate TNFα-induced apoptosis in murine myoblasts and preadipocytes, and to enhance Apo2L/TRAIL-induced apoptosis in human colon carcinoma cells." (PMID 23091403, 2012). "For example, TNF-α and IL-1β are potent stimulators for MMP9 in astrocytes, and IL-6 induces overexpression of MMP9 in human colon carcinoma cells, and TNF-α and IL-1β also can induce activation of NF-κB." (PMID 22529521, 2012). "The NPA methods were tested on two transcriptomic data sets: normal human bronchial epithelial (NHBE) cells treated with the pro-inflammatory signaling mediator TNFα, and HCT116 colon cancer cells treated with the CDK cell cycle inhibitor R547." (PMID 22651900, 2012). "We demonstrated here that combined treatment of TNFα and IFN-γ, two physiologic cytokines of the host immune system, effectively sensitized metastatic human colon carcinoma cells to TRAIL-induced apoptosis." (PMID 21264227, 2011). "The functional significance of TNFα- and IFN-γ-producing T lymphocyte immunotherapy in combination with TRAIL therapy in suppression of colon carcinoma metastasis was determined in an experimental metastasis mouse model." (PMID 21264227, 2011). "Our above data demonstrated that TNFα, when used in combination with IFN-γ, can sensitize metastatic human colon carcinoma cells to TRAIL-induced apoptosis." (PMID 21264227, 2011). "Taken together, our observations suggest that TNFα and IFN-γ sensitize the metastatic colon carcinoma cells to TRAIL-induced apoptosis at least partially through repressing Bcl-xL expression." (PMID 21264227, 2011). "C-reactive protein (CRP), albumin, IL-1α, IL-1β, IL-6, IL-8, IL-10, TNF-α, midkine, VEGF-A, VEGF-C, leptin, adiponectin, and ghrelin serum levels are studied in 126 colon cancer patients and 36 healthy subjects." (PMID 20920199, 2010). "In this paper we apply a fuzzylogic framework to the analysis of a large, systematic dataset describing thedynamics of cell signaling downstream of TNF, EGF, and insulin receptors inhuman colon carcinoma cells." (PMID 19343194, 2009). "Our findings indicate that collagen does not significantly impact TNF-α expression in HCT116 colon carcinoma cells or CCD-18Co normal colon cells." (PMID 40699763, 2025).
colon carcinoma (continued). "published that TNF-α blockers not only ameliorate the anti-tumor effect of anti-PD-1 and anti-CTLA-4 combination, but at the same time, reduce irAEs in a preclinical mouse model of colon cancer." (PMID 40433358, 2025). "While CaMKII-mediated MLKL phosphorylation executes necroptosis in colon cancer cells treated with OSW-1 and smooth muscle cells treated with TNF-α plus z-VAD, it was found to facilitate autophagic flux and protect cells from starvation-induced death in L929 mouse fibroblast cells." (PMID 40329104, 2025). "Collectively, these findings suggest that compound 27 in TP may contribute to the prevention of colon cancer by forming a stable complex with TNF-α, thereby downregulating TNF-α and inhibiting the NF-κB signaling pathway." (PMID 40607420, 2025). "Another study proposed that mechanisms of quercetin in treating colon cancer may involve inhibition of the TLR4/NF-κB signaling pathway as well as the reduction in the production of inflammation factors, including TNF-α, Cox-2, and IL-6." (PMID 38243957, 2025). "Moreover, investigating the cellular origins of ligands such as TNF and TGF-β, which are pivotal in triggering the metastatic cascade, and their interactions with metastatic colon cancer cells, is crucial." (PMID 40954257, 2025). "Ultimately, a deeper understanding of TNF-α signaling and its interactions with other oncogenic pathways, such as NF-κB, Wnt/β-catenin, and STAT3, will pave the way for more effective and personalized treatments for colon cancer." (PMID 40558596, 2025). "However, CD8+ TILs that have been detected in glioma and colon cancer showed increased activation and cytotoxicity, as indicated by elevated levels of interferon gamma (IFN-γ), tumor necrosis factor alpha (TNF-α), and IL-2 protein or RNA synthesis." (PMID 39537934, 2024). "Studies in patients with systemic lupus erythematosus had shown that TNF-α boost PD-L1-expression in monocytes and this upregulation is likely to occur through TNF-α-mediated activation of NF-κB and ERK1/2 pathways as deciphered from studies in human colon cancer HCT116 cells." (PMID 39445017, 2024). "PTX3 mRNA expression and protein levels were significantly induced by IL-1β and TNF-α in human and mouse fibroblasts but not in colon cancer cells." (PMID 38243273, 2024). "TAM may also release tumor necrosis factor (TNF), and the synergistic effect of TNF and TGF-β has been shown to enhance EMT in colon cancer." (PMID 38244071, 2024). "Induction of colon cancer by AOM caused elevation of IL-6, IL-12p70, and TNF-α in normal diet+AOM compared to normal diet control." (PMID 39845239, 2024). "LPS increased COX2 and TNFSF10 mRNA levels but did not exhibit significant effect on HuA, LEPTIN and TNF mRNA levels in the human colon cancer cells." (PMID 37705049, 2023). "Our in vivo results suggested that anti TNF-α Ab, infliximab could inhibit mast cell accumulation in the colon, resulting in decreased levels of TNF-α and attenuated colon cancer in AOM/DSS mice." (PMID 37185713, 2023). "The combination strategy was evaluated in mice bearing colon carcinoma cells (CT26) tumors following their weight, tumor volume, interferon-gamma (IFN-γ), and tumor necrosis factor-alpha (TNF-α) levels in the serum and produced by splenocytes exposed to CT26 tumor cells." (PMID 36046055, 2022). "The enhancement effect of 3D culture on the TNFα was not unique to FLS or a particular set of genes since the effect was reproduced in the human colonic carcinoma cell line HCT-8 with enhancement of all the measured genes." (PMID 36045678, 2022). "In the AOM/DSS model, the activation of TNF-α has been demonstrated to be caused by DSS rather than AOM, and TNF-α accelerates progression of colon carcinomas by increasing COX-2 expression level and inhibiting the Wnt signaling pathway." (PMID 35865942, 2022).
colon carcinoma (continued). "According to the current research, administering LME to colon cancer-model rats significantly reduced their levels of AFP, CEA, and CA 19.9, as well as immune-inflammatory markers (TNF-α and IL-1β) matched with the development of apoptotic biomarker (CD4+), compared to the control group." (PMID 36294905, 2022). "Transcriptomic analysis of human colon tumors with high fusobacterial RNA levels revealed the Fusobacterium‐induced genes, PTGS2 (COX‐2), IL1β, IL6, IL8, and TNF (TNF‐α), indicating an NF‐κB‐driven proinflammatory response associated with colorectal carcinogenesis." (PMID 35244982, 2022). "Furthermore, nuclear PKM2 was reported to regulate the production of TNF-α, IL-1β, MMP-2, and MMP-9 in colon cancer cells and to activate inflammasomes." (PMID 35256696, 2022). "In this study, we have demonstrated that circulating NF-κB, TNF-α, IL-6, PTX-3, PCT, and CRP levels in breast and colon cancer were significantly higher than in control groups and NF-κB levels were positively correlated with IL-6, PTX-3, PCT, and CRP in all patients." (PMID 33776564, 2021). "The circulating IL-6, TNF-α, TRAIL level in breast and colon cancer may be a biomarker of postoperative progression or recurrence." (PMID 33776564, 2021). "IBD patients have chronic inflammation which is an underlying risk factor for colon cancer, and mouse models demonstrate that tumor necrosis factor α (TNF-α), a target of IBD treatments, plays a critical role in development of inflammation-induced colon cancer." (PMID 33607938, 2021). "The serum NF-κB, TNF-α, IL-6, PTX-3, PCT, and serum CRP concentration was significantly higher, and the serum sTRAIL concentration was significantly lower in the patients with breast and colon cancer than in healthy controls." (PMID 33776564, 2021). "Furthermore, proteasome inhibition suppresses necroptosis competency, as shown in TNFα/zVAD-fmk/IAP antagonist treated macrophages and HT29 colon cancer cells." (PMID 34168123, 2021). "Notably, our findings are in accordance with the results of the current study which shows elevated levels of TNF-a, IL-6, and VEGF in patients suffering from colon cancer." (PMID 34096454, 2021). "This is consistent with the finding that even TNF-α (NF-κB inducer)-primed colon carcinoma HCT116 cells failed to protect constitutive NF-κB activation, in response to TAT-FADD treatment." (PMID 32961826, 2020). "The treatment with CyCl significantly induced the nuclear translocation of Nrf2 in colon cancer cells with or without TNF-α stimulation." (PMID 32230772, 2020). "The addition of CyCl to colon cancer cells resulted in a significant increase in mRNA and protein levels of the expression of antioxidant enzymes with or without TNF-α stimulation." (PMID 32230772, 2020). "Human γδ T cells stimulated by zoledronate produced higher IFN-γ, TNF-α, granzymes, and TRAIL, thus enhancing the killing effect on the colon cancer stem cells, which was mediated by the granule exocytosis pathway and was related to the expression of isoprenoid by tumor cells." (PMID 33013819, 2020). "Human colon cancer HT-29 cells were treated with these compounds for 2 h prior to the treatment of necroptotic stimuli (TNFα, Smac mimetic and z-VAD), which are widely used to trigger TNF-induced necroptosis." (PMID 33364238, 2020). "In line with its role as an inflammation amplifier, the interleukin expression it is upregulated by TNFα in ESCC and colon cancer cell lines and, in a positive feed-back loop, activates NFκB in esophageal tumors and upregulates TNFα expression and secretion in the colon." (PMID 33020452, 2020). "CyCl treatment concomitantly inhibited NF-κB activation and increased Nrf2 translocation in colon cancer cells with or without TNF-α stimulation." (PMID 32230772, 2020). "Furthermore, takinib + TNF treatment of the colon cancer cell line, COLO205, showed robust induction of apoptotic proteins in response to TAK1 inhibition and TNF stimulation." (PMID 32523651, 2020).